TNF (tumor necrosis factor)
Diseases named in the same sentence as TNF in open-access papers (continued):
Sharing a sentence is not in itself a finding about the gene and the disease.
structural epilepsy (1 paper, 2020). A type of epilepsy that is conceptualized as having a distinct structural brain abnormality that has been demonstrated to be associated with a substantially increased risk of epilepsy in appropriately designed studies. "Increased expression levels might result in excessive inflammatory signaling in dogs with structural epilepsy taking into account that TLR4 activation results in enhanced generation and release of pro-inflammatory cytokines including interleukin-1β and tumor-necrosis factor α." (PMID 31959173, 2020).
sudden infant death syndrome (1 paper, 2015). Unexpected death in infancy which remains unexplained following autopsy, review of the medical history, and investigation of the death circumstances and death scene. "Tumor necrosis factor-α (TNF-α) is a key pro-inflammatory cytokine which could play a role in several of the mechanisms proposed to explain sudden infant death syndrome (SIDS)." (PMID 26284064, 2015).
Takotsubo syndrome (1 paper, 2021). "IL-2, IL-4, IL-10, IFN-γ and TNF-α at admission were shown to be significantly higher in patients with acute Takotsubo syndrome compared to patients with AMI, conversely, IL-6 was much higher in AMI patients." (PMID 34095448, 2021). "In addition, IL-10 likely prevents cardiomyocyte apoptosis via TNF-α, accounting for the functional recovery in patients with Takotsubo syndrome." (PMID 34095448, 2021). "TNF-α and IFN-γ (both pro-inflammatory cytokines) are significantly elevated in Takotsubo syndrome compared to AMI, also likely reflecting the inflammatory substrate of Takotsubo syndrome." (PMID 34095448, 2021).
tapeworm infection (1 paper, 2022). "In addition, the gene expression profile of the pro- and anti-inflammatory cytokines (TNF-α, IL-1β, IL-6 and IL-10) was evaluated by Real-Time PCR to determine the immune response within the CNS to the tapeworm infection." (PMID 35286352, 2022).
Theileriosis (1 paper, 2014). "By demonstrating a mechanistic link of TNFα signaling to the established motility regulator MAP4K4, we provide an explanation for how TNFα expression contributes to Tropical Theileriosis pathogenesis and how TNFα production could be linked with the progression of tumors to invasive cancers." (PMID 24626571, 2014). "Together, we highlight the potential functional significance of TNFα signaling in Tropical Theileriosis, and we revealed a pathogen dependent-mechanism controlling oncogene expression and function to promote invasive motility of its host cell." (PMID 24626571, 2014). "Thus, our findings reveal how the intracellular Theileria parasite can influence morphology and behavior of its host cell in a way that suits its propagation and highlight a novel function of chronic TNFα production for the pathogenesis of Tropical Theileriosis." (PMID 24626571, 2014).
thymic carcinoma (1 paper, 2017). Thymic carcinoma (TC) is a type of thymic epithelial neoplasm characterized by a high malignant potential. "However, combined application of CQ and Z-VAD-FMKa rescued significant numbers of neoplastic pTECs and thymic carcinoma 1889c cells from TNFα induced cell death." (PMID 29163772, 2017). "By contrast, the EF24 treated control thymic carcinoma cell line, 1889c, and HaCaT cells could be partially rescued from TNFα-induced cell death by either Z-VAD-FMK or Necrostatin1 or both inhibitors." (PMID 29163772, 2017). "By contrast, cFLIP-depleted cells of the 1889c thymic carcinoma cell line could partially be rescued from TNFα-induced cell death by inhibitors of caspases, necroptosis and autophagy, suggesting that cFLIP in 1889c carcinoma cells may regulate a broader spectrum of cell death-inducing targets." (PMID 29163772, 2017).
treatment resistant depression (1 paper, 2023). Unipolar depression that does not respond to commonly used treatments, typically defined as lack of response to at least two appropriate antidepressant treatments. "Treatment-resistant depression (TRD) in particular is associated with a heightened inflammatory response, and treatment with the anti-inflammatory tumor necrosis factor-alpha (TNF-α) antagonist, infliximab, has been shown to improve TRD." (PMID 37206541, 2023).
trichotillomania (1 paper, 2017). A disorder characterized by repetitive pulling out of one's hair resulting in noticeable hair loss; the individual experiences a rising subjective sense of tension before pulling out the hair and a sense of gratification or relief when pulling out the hair. "The current study examined a range of salivary inflammatory markers (IL-1β, IL-6, IL-8, and TNF-α) in a sample of patients with trichotillomania, and whether inflammation related to symptom severity and other clinical measures." (PMID 29920483, 2017).
Ts (1 paper, 2024). "Here, helminth Trichinella spiralis (Ts) infection was shown to protect against TNF-α- and IFN-γ-induced shock." (PMID 38727220, 2024). "Similarly, we observed increased LDH, ALT, AST, BUN, and ferritin in the serum of the control mice injected with TNF-α and IFN-γ compared with the blank group, whereas Ts infection significantly reduced the levels of all laboratory parameters elevated by TNF-α and IFN-γ." (PMID 38727220, 2024).
tubular adenocarcinoma (1 paper, 2025). An infiltrating adenocarcinoma in which the malignant cells form tubular structures. "TNF-α in tubular adenocarcinoma showed a particularly robust association with CA19-9 (rho = 0.797, p < 0.001), indicating that these tumors may rely more heavily on inflammatory mediators alongside tumor marker elevation." (PMID 40299527, 2025). "Concordant with this, TNF-α in tubular adenocarcinoma cases was tightly linked to CA19-9, whereas in poorly cohesive carcinomas TNF-α was strongly correlated with CEA and CA72-4." (PMID 40299527, 2025). "When the WHO classification was applied, tubular adenocarcinoma had the highest median TNF-α at 9.60 [3.02–21.70] pg/mL, followed by poorly cohesive carcinoma at 7.52 [3.53–12.39] pg/mL, carcinoma NOS at 5.10 [3.56–9.30] pg/mL, and adenocarcinoma NOS at 3.86 [1.92–9.30] pg/mL." (PMID 40299527, 2025). "Similarly, when analyzing by WHO histopathological categories, we found that tubular adenocarcinomas (which largely correspond to Lauren intestinal-type) exhibited the highest TNF-α median values, whereas poorly cohesive carcinomas (related to the diffuse type) had more moderate TNF-α levels." (PMID 40299527, 2025).
type III hypersensitivity reaction (1 paper, 2014). "It has been suggested that anti-TNF-α/TNF-α immune complexes could be deposited in small capillaries, where they activate complement and thereby trigger a type III hypersensitivity reaction." (PMID 25544845, 2014).
Urea (1 paper, 2020). "In Zucker Obese rats, Cl and IL-1beta were found to be inversely correlated; Ca2+ and Fe were directly correlated with Urea and TNF-alpha, respectively." (PMID 33306695, 2020).
urethral fistula (1 paper, 2024). "Regarding medical management, we note that two patients were managed conservatively, without surgery, with tumor necrosis factor inhibitor (TNFi) biologic medications, one of whom (a urethral fistula) healed." (PMID 38918216, 2024).
Urethral stricture (1 paper, 2025). Narrowing of the urethra associated with inflammation or scar tissue. "In a rat urethral fibrosis model induced by TGF-β1, miR-146a-enriched exosomes derived from TNF-α-treated HUMSC suppressed urethral stricture by reduction of IL-1β/-6, IL-1 receptor-associated kinase 1 (IRAK1), TNF receptor-associated factor 6 (TRAF6), and NF-κB levels in target cells." (PMID 40676634, 2025).
urinary system tumors (1 paper, 2024). "In urinary system tumors, recent reports have revealed the RNF26/CBX7 axis, where RNF26 promotes the degradation of CBX7, regulating the TNF signaling pathway in ccRCC and promoting ccRCC tumor growth." (PMID 38890443, 2024).
uterine disorder (1 paper, 2013). A non-neoplastic or neoplastic disorder that affects the uterine corpus or the cervix. "PGF metabolites were higher in cows with postpartum uterine disorders, possibly due to TNF-α controlled endometrial PG synthesis." (PMID 24209779, 2013).
Varicose veins (1 paper, 2022). Enlarged and tortuous veins. "Some inflammatory and prothrombotic markers (e.g., IL-6, TNF-α, vWF, and PAI-1) has been reported to be significantly elevated in varicose veins." (PMID 35498031, 2022).
vascular hypertrophy (1 paper, 2020). "TNFα deficiency improved EDR and lowered cardiac and vascular hypertrophy with a mild reduction in SBP (152 ± 4 vs. 167 ± 5 mmHg in DOCA group, p < 0.05) in DOCA mice." (PMID 32190663, 2020).
Vitamin B1 deficiency (1 paper, 2021). "Vitamin B1 deficiency causes overexpression of pro-inflammatory cytokines such as interleukin (IL)-1, IL-6, and tumor necrosis factor-alpha (TNF-α) as well as increased expression of CD40 and CD40 ligand by microglial cells and astrocytes, which eventually leads to the death of neuron cells." (PMID 33923999, 2021).
vitamin B2 deficiency (1 paper, 2019). "Vitamin B2 deficiency resulted in an increased methylation of histones on genes encoding pro-inflammatory cytokines, like tumor necrosis factor-alpha and IL-1beta, highlighting a role for vitamin B2 deficiency in immune signaling." (PMID 30809153, 2019).
vitamin D (1 paper, 2014). "Upon A. fumigatus exposure, vitamin D deficiency led to enhanced and sustained expression of TNF-α, IL-1β, IL-6, CXCL1 and CCL3 both in vivo and in vitro." (PMID 24926881, 2014).
VRSA infection (1 paper, 2023). "In accordance, VRSA infection provoked upregulated relative mRNA expression levels of pro-inflammatory genes (IL-1β, TNF-α, and IL-6) and apoptosis-associated genes (caspase-3, caspase-9, and Bax)." (PMID 38282617, 2023).
Weil's disease (1 paper, 2024). A jauncice caused by severe leptospirosis. "Patients with Weil’s disease may present with a cytokine storm characterized by high levels of IL-6, IL-10, and tumor necrosis factor-alpha (TNF-α)." (PMID 38398036, 2024).
Wolfram syndrome (1 paper, 2021). Wolfram syndrome (WS) also known as DIDMOAD, is a neurodegenerative disorder characterized by type I diabetes mellitus (DM), diabetes insipidus (DI), sensorineural deafness (D), bilateral optical atrophy (OA) and neurological signs. "As previously reported, markers of inflammatory cytokines and oxidative stress, such as IFN-γ, IL-1β, TNF-α, and isoprostane, were elevated in subjects with Wolfram syndrome." (PMID 34185708, 2021). "As compared with levels previously reported in heathy subjects, levels of IFN-γ, TNF-α, IL-1β, MIP-1β, MIP-3α, IL-21, and isoprostane were higher in study subjects with Wolfram syndrome." (PMID 34185708, 2021).
xanthomatosis (1 paper, 2014). A condition marked by the development of widespread xanthomas, yellow tumor-like structures filled with lipid deposits. "Interestingly, we observed that both forms of normolipidaemic xanthomatosis were associated with a common inflammatory pattern characterized by increased CRP and plasma levels of classical pro-inflammatory cytokines (IL-6 and TNFα)." (PMID 24428816, 2014).
yang deficiency (1 paper, 2022). Yang deficiency is a concept from traditional Chinese medicine. "The symptomatic gene targets for Yang deficiency (KAT2B, NFKB2, CREBBP, GTF2H3) or Yin deficiency (JUNB, JUND, NGLY1, TNF, RAF1, PPP1R15A) were potentially discovered." (PMID 35341155, 2022).
Yersinia enterocolitica infection (1 paper, 2015). "Alternatively, others have shown that histamine signaling via H2R in Peyers patches is protective in murine models of Yersinia enterocolitica infection and histamine suppresses LPS-mediated TNFα secretion by human PBMCs." (PMID 25723478, 2015).
tumor (12,794 papers, 1988 to 2026). "Stratified analyses showed a lower frequency of the IL6 rs1800795 C allele and TNF rs1800629 GA genotype in high-grade and muscle-invasive tumors, suggesting potential associations with reduced tumor aggressiveness." (PMID 42074005, 2026). "For instance, VNS can suppress the production of key protumorigenic cytokines such as IL‐6, IL‐1β, and TNF‐α—critical drivers of tumor‐associated inflammation—thereby enhancing T cell‐mediated immune responses." (PMID 41583906, 2026). "YWHAH emerged as a key TNF-associated, m6A-regulated gene, with elevated expression in naive/GC B cells, interleukin (IL)-1β+ tumor-associated macrophages, and differentiated epithelial cells." (PMID 41705255, 2026). "CD4+ T cell activation in the spleen was directly linked to increased IFN-γ and TNF-α production by CD8+ T cells within the tumor microenvironment, fostering a reduction in Tregs and mitigating local immunosuppression." (PMID 41522339, 2026). "Cytokines such as interleukin-6 (IL-6), tumor necrosis factor-alpha (TNF-α), IL-1β, and IL-8 are implicated in enhancing tumor growth, immune evasion, and metastasis." (PMID 41497141, 2026). "For example, Bifidobacterium strains have been genetically modified to carry plasmids that encode for tumor necrosis factor-alpha (TNF-α), a cytokine with potent anti-tumor activity." (PMID 41355950, 2026). "As shown, M1 macrophage markers-including IL-1β, IL-6, iNOS, and TNFα-were significantly increased in THP-1 cells co-cultured with N4BP1-deficient TSCC cells compared to those co-cultured with control tumor cells." (PMID 41513619, 2026). "In pancreatic ductal adenocarcinoma, IL-17A promotes tumor progression by inducing the differentiation of cancer-associated fibroblasts via IL-17RA and TNF signaling, creating a tumor-promoting stromal environment." (PMID 40536951, 2026). "According to a previous pan-cancer single-cell transcriptomic atlas of tumor-infiltrating myeloid cells, the proportion of TNF+ MCs and VEGFA+ MCs was significantly associated with cancer prognosis." (PMID 40932351, 2026). "Additional inhibition and immunofluorescence analyses suggested that iNOS and TNF-α-associated mechanisms contributed to these tumor-suppressive effects." (PMID 42197424, 2026). "Biomarkers such as 8-hydroxy-2'-deoxyguanosine, malondialdehyde, F2-isoprostanes, C-reactive protein, interleukin-6, and tumor necrosis factor-α were frequently associated with tumor stage, prognosis, and treatment response." (PMID 41900943, 2026). "Curcumin was shown to neutralize the oxidative stress of tumor cells, restore NF-κB activity, and reactivate the TNF-α signaling pathway, thus causing the enhancement of T cells’ ability to resist apoptosis." (PMID 40940890, 2025). "Cluster 2, characterized by hypomethylation of genes like RORC, S100A13, and TNF, correlates with higher tumor mutation burden (TMB) and better immunotherapy responses, as higher TMB generates neoantigens that activate immune responses." (PMID 41029427, 2025). "In response to higher levels of HA synthesis and fragments in tumor-associated cells, neutrophils and macrophages produce pro-inflammatory cytokines (IL-1, IL-6, IL-22, and TNF-α) which predispose individuals to cancer mutations." (PMID 40723879, 2025). "Tumor necrosis factor α (TNFα), also secreted by the MDSCs and M1 macrophages described later, is theorized to play a role in the cachectic effects associated with tumor progression." (PMID 40427098, 2025). "Since IL-1β, IL-6, and TNF-α are well-established mediators of tumor-associated inflammation, their downregulation is mechanistically relevant." (PMID 41470183, 2025). "The secretion of TNF by macrophages is decreased in patients with FLT3-ITD mutations, but TNF exerts a dual effect on tumor cells." (PMID 40861464, 2025).
tumor (continued). "The authors of this study suggest that this encourages migration until the tumor reaches a critical mass, at which point tumor-secreted TGFβ disrupts osteocyte cilia and associated TNFα secretion." (PMID 40301543, 2025). "For instance, tumor-associated macrophages (TAMs) secrete pro-inflammatory cytokines such as IL-6 and TNF-α, triggering neuroinflammatory responses." (PMID 40276074, 2025). "In our study, we found that the environment of GBM cells exposed to MSCMel presented reduced levels of IFNγ, TNFα and IL-1β, and this condition was associated with a less aggressive tumor phenotype." (PMID 40083939, 2025). "None of the inflammatory markers or staging variable demonstrated a significant independent association with TNF-α after controlling for the tumor markers." (PMID 40299527, 2025). "These cells produce elevated levels of IFN-γ and numerous other cytokines (namely TGF-β, TNF-α, and IL-2), thereby activating the M1 tumor-associated macrophages and cytotoxic T cells." (PMID 40136347, 2025). "This is consistent with previous observations, where elevated TNF-α was linked to increased tumor burden and poorer outcome in patients with r/r FL." (PMID 40536814, 2025). "In this study, we investigated the expression levels of IL-2, IL-10, IL-6, and TNF-α and assessed their associations with clinical and pathological tumor features." (PMID 40869161, 2025). "Animal studies showed that upregulation of inflammatory cytokine pathways such as Interleukin-6 (IL-6), IL-8, and Tumour Necrosis Factor (TNF)-α is linked to PCa tumour growth." (PMID 40941553, 2025). "IFN-γ and TNF-α, known to inhibit tumor cell proliferation, attenuate tumor-associated angiogenesis, and hinder multistage carcinogenesis, were significantly upregulated after treatment, particularly in the combined therapy group (p < 0.01)." (PMID 40670983, 2025). "In contrast, cytokines, such as TNF-α, are generally associated with a pro-inflammatory, tumor-suppressive macrophage phenotype, which can enhance the ability of the immune system to fight against the tumor." (PMID 40002754, 2025). "AurA deficiency or inhibition decreased IL-6 and TNF production in β-glucan-trained BMDMs upon rechallenge by LPS or supernatant from tumor cells." (PMID 40920087, 2025). "Gene ontology analysis revealed associations with tumor necrosis factor (TNF) responses and vascular development within tumor-infiltrating DC." (PMID 39932553, 2025). "We demonstrated that VS-induced SNHL was linked to increased secretion of TNF-α, IL-2R, CD163, eotaxin, and HGF, while larger tumor size was associated with higher levels of TNF-α, TNF-R2, IL-1α, IFN-α, MIP-1β, and IL-21 secretion." (PMID 39923035, 2025). "Salmonella carrying a prokaryotic expression vector encoding TNF-α demonstrated activity as a tumor-targeting anticancer agent and adjuvant in syngeneic murine tumor models." (PMID 40528960, 2025). "In BC, chronic TNF secretion by cancer-associated macrophages and stromal cells creates a pro-inflammatory environment that supports tumor growth." (PMID 40547917, 2025). "Tumor-associated neutrophils (TANs) produce high levels of TNF, inducible nitric oxide synthase (iNOS), NO, and H2O2, damaging DNA and inducing genetic instability." (PMID 40940764, 2025). "In combination with Porphyromonas gingivalis, Tannerella forsythia also promotes the overexpression of GLUT1/GLUT4 through TNF-α and ROS signaling, a hallmark of tumor aggressiveness." (PMID 41155306, 2025). "IL-1β, IL-18, and TNF-α are known to be associated with tumour invasion, progression, and metastatic potential." (PMID 40430084, 2025). "Larger tumor size was associated with elevated levels of TNF-α (r = 0.290, P = 0.009), TNF-R2 (r = 0.318, P = 0.022), IL-1α (r = 0.309, P = 0.026), IFN-α (r = 0.349, P = 0.007), MIP-1β (r = 0.306, P = 0.031), and IL-21 (r = 0.295, P = 0.032) in VS-CM." (PMID 39923035, 2025).